ADAM17 (ADAM metallopeptidase domain 17)
Diseases named in the same sentence as ADAM17 in open-access papers (continued):
Sharing a sentence is not in itself a finding about the gene and the disease.
ovarian carcinoma (35 papers, 2011 to 2026). A malignant neoplasm originating from the surface ovarian epithelium. "In summary, our results underline that inhibition of ADAM17 in combination with olaparib leads to a significant reduction in cell viability and a subsequent increase in apoptosis in all ovarian cancer cell lines." (PMID 39506058, 2024). "Systematic analysis of large data portals identifies the ADAM17 gene as one of the NOTCH-associated genes overexpressed in ovarian cancer tissues compared with normal ovaries, generally associated with advanced cancer stages and with poor PFS and OS times." (PMID 36140519, 2022). "ADAM17 promotes the malignant progression of ovarian cancer and causes chemo-resistance by mediating ADAM17-dependent shedding of AREG, HB-EGF, IL-6Rα, TNF, TNFR1-α, TGFα and activating the EGFR signaling pathway." (PMID 36466812, 2022). "The aim of this work is to evaluate the relevance of ADAM17 as a potential diagnostic blood-based biomarker in ovarian cancer." (PMID 34771725, 2021). "In addition, a recent study investigated ADAM17 protein in serum as a diagnostic biomarker in ovarian cancer." (PMID 36140519, 2022). "To investigate if ADAM17 could function as a novel diagnostic marker for ovarian cancer at primary diagnosis, we collected and characterized serum of 117 ovarian cancer patients." (PMID 34771725, 2021). "Interestingly, it has been shown, that high expression levels of HB-EGF were significantly associated with the clinical outcome of ovarian cancer patients and correlated with ADAM17 expression." (PMID 29662625, 2018). "In a xenograft model of ovarian cancer, administering a monoclonal antibody targeting ADAM17 effectively blocked the shedding of its substrates, which significantly reduced tumor growth." (PMID 41050403, 2025). "Research has demonstrated that enzymatically active ADAM17 is secreted in EVs from ovarian cancer cells following chemotherapy." (PMID 40757000, 2025). "Specifically, ADAM17 increases its activity when ovarian cancer cells are treated with cisplatin, leading to amphiregulin (AREG) shedding and subsequent EGFR signaling." (PMID 41050403, 2025). "In line with our previous studies focusing on chemoresistance in ovarian cancer, we showed strong combinatorial effects of ADAM17 inhibition and cisplatin treatment in cervical cancer." (PMID 39286024, 2024). "We have reported an increase in ADAM17 activity and substrate release in response to cisplatin treatment in ovarian cancer cell lines and spheroids." (PMID 39286024, 2024). "In this study, we demonstrated that inhibition of ADAM17 significantly improved the treatment response of olaparib in ovarian cancer." (PMID 39506058, 2024). "This study investigated the function of ADAM17 in mediating resistance to olaparib treatment in ovarian cancer." (PMID 39506058, 2024). "A disintegrin and metalloproteases 17 (ADAM17) is overexpressed in many tumors such as lung, breast and ovarian cancer and plays a crucial role in tumor proliferation, progression and migration." (PMID 39506058, 2024). "Our study proposes ADAM17 inhibition sensitizing ovarian cancer to olaparib treatment and improving treatment response." (PMID 39506058, 2024). "Based on the activation z-score, 49791 analyses for ADAM17 were identified, providing the rational of human ovarian cancer 8547 as our analysis target because it has the highest combination of significance -log10 (p-value) and activation z-score of ADAM17." (PMID 38341954, 2024). "The results suggest that ADAM17 is a promising target in overcoming resistance mechanisms in ovarian cancer and is worth investigating in further studies." (PMID 39506058, 2024). "Another study reported that ADAM17 levels were significantly elevated in the serum and ascites of patients with ovarian cancer, thus serving as a serum tumor marker for the early detection of this type of cancer." (PMID 37175410, 2023).
ovarian carcinoma (continued). "The ADAM17 substrates Nectin-4 and HB-EGF appear to be promising markers for the detection of early stages of ovarian cancer and are associated with prognostically favorable parameters, such as early FIGO stage and successful tumor debulking." (PMID 36497350, 2022). "It was shown that Nectin-4, HB-EGF, and AREG are proteolytically cleaved by the metalloprotease ADAM17 and represent essential factors in the regulation of ovarian cancer." (PMID 36497350, 2022). "In a previous study, we already proposed a disintegrin and metalloprotease 17 (ADAM17) as a tumor marker in the context of ovarian cancer and demonstrated its importance in the detection of early stages." (PMID 36497350, 2022). "In particular, the ADAM17 substrates AREG and TGF-alpha were found in the ascites of ovarian cancer patients, suggesting high activity of ADAM17 in this tumor." (PMID 36140519, 2022). "ADAM17 has been involved in ovarian cancer development, progression and cell resistance to cisplatin." (PMID 36140519, 2022). "Tissue microarrays from 309 ovarian cancer patients enrolled in the MITO16A/MANGO-OV2 clinical trial were analyzed by immunohistochemistry for ADAM17 protein expression." (PMID 36140519, 2022). "To answer the question, if ADAM17 levels correlate with histological subtypes of ovarian cancer, we compared ADAM17 levels of 117 patients including 84 serous, 18 endometrioid, 6 clear cell, and 9 other histological subtypes." (PMID 34771725, 2021). "In this study, the cell culture experiments confirmed that ADAM17 is detectable in the supernatant of ovarian cancer cell lines and patient-derived cells after culturing." (PMID 34771725, 2021). "In other studies, tumor spheroids derived from ovarian cancer cell lines or primary patients’ cells were sensitized to cisplatin treatment by using an inhibitor of A disintegrin and metalloprotease 17 (ADAM17), named GW280264X, to overcome resistance." (PMID 34684841, 2021). "An enhanced processing of these factors and high expression of ADAM17 in tumors has been shown in a variety of solid tumors including ovarian cancer." (PMID 34771725, 2021). "ADAM17 level was significantly increased in ovarian cancer patients compared to an age-matched control group (p < 0.0001)." (PMID 34771725, 2021). "Increased expression levels of the ADAM17 protein have been described in many solid tumors, including lung, gastric, renal, colon, pancreatic, and ovarian cancer." (PMID 34771725, 2021). "Here, we tested the effect of the ADAM17 inhibitor GW280264X in combination with cisplatin on ovarian cancer cells in 2D and 3D." (PMID 33922533, 2021). "In all investigated supernatants, we detected ADAM17 levels between 1500 pg/mL and 3500 pg/mL and thus confirmed that ADAM17 is detectable in conditioned medium of ovarian cancer cell lines and patient-derived cells." (PMID 34771725, 2021). "In summary, ADAM17 appears to be a promising screening marker for detecting early-stage ovarian cancer." (PMID 34771725, 2021). "For the first time, the present study identified the metalloprotease ADAM17 in the serum of ovarian cancer patients and indicates a possible application as a marker for early-stage disease." (PMID 34771725, 2021). "When ADAM17 was inhibited in ovarian cancer cell lines using either anti-ADAM17 antibody D1 or GW280264X, the cancer cells were sensitised to cisplatin-induced apoptosis, therefore significantly reducing cell viability." (PMID 33904577, 2021). "In summary, we demonstrate that ADAM17 inhibition is a promising treatment strategy in ovarian cancer." (PMID 33922533, 2021). "For this approach at primary diagnosis drawn serum and ascites fluid from 10 ovarian cancer patients were analyzed by ADAM17 sandwich ELISA." (PMID 34771725, 2021). "We have recently shown that the ADAM17 protein is expressed by ascites derived from ovarian cancer cells." (PMID 34771725, 2021).
ovarian carcinoma (continued). "In the present study, ADAM17 was detected in the culture supernatant of ovarian cancer cell lines and primary cells." (PMID 34771725, 2021). "This is the first report describing ADAM17 detection in serum and ascites fluid of ovarian cancer patients." (PMID 34771725, 2021). "For a variety of solid tumors, including ovarian cancer, elevated levels of ADAM17 have been detected by immunohistochemistry, flow cytometry, and real-time PCR, respectively." (PMID 34771725, 2021). "In this study, we achieved detection of ADAM17 in serum as well as in ascites fluid of ovarian cancer patients." (PMID 34771725, 2021). "In a translational approach, a cohort of 117 well-characterized ovarian cancer patients was assembled and ADAM17 levels in serum and corresponding ascitic fluid were determined at primary diagnosis." (PMID 34771725, 2021). "With the aim to identify the upstream regulators of AREG and transforming growth factor-alpha (TGF-α) release, we focused our work on ADAM17, a metalloprotease, highly expressed in ovarian cancer and the major sheddase of these cell membrane hosted ligands." (PMID 29662625, 2018). "Taken together, inhibition of ADAM17 sensitized patient-derived ovarian cancer cells to cisplatin treatment." (PMID 29662625, 2018). "For ovarian cancer it has been demonstrated that an ADAM17-antibody reduces tumor growth in a xenograft model; using the same antibody we confirmed the ADAM17 selectivity of AREG-shedding in our ovarian cancer cells." (PMID 29662625, 2018). "For most solid tumors, including lung, gastric, renal, colorectal, pancreatic and ovarian cancer, high expression levels of ADAM17 protein were shown." (PMID 29662625, 2018). "Inhibition by GW alone already significantly triggered apoptosis compared to control treatment (NaCl, DMSO) by about 12 % (p=0.023), suggesting a critical role of ADAM17 in survival of ovarian cancer cells." (PMID 29662625, 2018). "In the majority of ovarian cancer cells cisplatin treatment resulted in enhanced ADAM17 activity, as shown by an increased shedding of AREG." (PMID 29662625, 2018). "As ovarian cancer patients are mostly affected by chemo resistance and recurrent disease, we aimed to elucidate the impact of ADAM17 in this particular tumor entity." (PMID 29662625, 2018). "In order to assess the effect of ADAM17 activation on downstream survival signaling in ovarian cancer cells, we investigated activation of the EGFR pathway." (PMID 29662625, 2018). "A disintegrin and metalloprotease 17 (ADAM17) is highly expressed in ovarian cancer and required for releasing epidermal growth factor receptor (EGFR) ligands like amphiregulin (AREG)." (PMID 29662625, 2018). "AREG was chosen as ADAM17 substrate because it was previously identified as one of the most abundant ADAM17 substrates in advanced ovarian cancer." (PMID 29662625, 2018). "In this study, we identified ADAM17 as an essential upstream regulator of AREG release under chemotherapeutic treatment in ovarian cancer cell lines and patient derived cells." (PMID 29662625, 2018). "Measuring apoptosis, we demonstrated that ADAM17 blockage sensitizes ovarian cancer cells to chemotherapeutic treatment." (PMID 29662625, 2018). "Here, we show that BPA and NP induce apoptosis in prostate and ovary cancer cell lines, in a process dependent on ADAM17 activation." (PMID 30065191, 2018). "We previously demonstrated that ADAM17/TACE activity is involved in motility of ovarian carcinoma cells." (PMID 21364949, 2011). "This indicates that EVs containing ADAM17 can transmit chemotherapy resistance in ovarian cancer." (PMID 40757000, 2025). "The purpose of this study is to evaluate whether inhibition of ADAM17 sensitizes ovarian cancer to treatment with olaparib, a PARPi, thereby bypassing resistance mechanisms and improving treatment response." (PMID 39506058, 2024).
ovarian carcinoma (continued). "Nevertheless, further studies are needed to elucidate the function of ADAM17 in mediating PARPi resistance mechanisms in ovarian cancer therapy, in order to identify suitable therapy formats including combinatorial treatments to overcome PARPi resistance in this devastating disease." (PMID 39506058, 2024). "In conclusion, the 2D cell culture results can also be demonstrated in a more complex model of ovarian cancer tumor spheroids: The effect of olaparib treatment is significantly enhanced by the additional inhibition of ADAM17, allowing a substantial dose reduction." (PMID 39506058, 2024). "Thus, we analyzed the effect of olaparib in combination with the ADAM17 inhibitor GW280264X in ovarian cancer using a 2D monolayer and a 3D spheroid model followed by a multicontent readout (viability, caspase activation and cytotoxicity)." (PMID 39506058, 2024). "Elevated ADAM17 expressions have been shown in most solid tumors, including ovarian cancer." (PMID 36497350, 2022). "We have previously shown that ADAM17 is elevated in the blood of ovarian cancer patients." (PMID 36497350, 2022). "In addition, NOTCH2, NOTCH3, DLL3, MAML1, and ADAM17 were determined as the five most relevant genes in ovarian cancer." (PMID 35136410, 2022). "Indeed, treatment of ovarian cancer cells with cisplatin in vitro resulted in enhanced ADAM17 activity, shedding of AREG and triggering of EGFR signaling." (PMID 36140519, 2022). "High levels of ADAM17 in serum and ascites fluid of patients with ovarian cancer may be used as a hematologic tumor marker for the detection of ovarian cancer." (PMID 36466812, 2022). "Indeed, ALCAM is expressed at the cell surface of ovarian cancer cells, and its shedding by ADAM17 is involved in cell migration and invasion." (PMID 36140519, 2022). "Indeed, ADAM17 protein in serum has been reported as a potential blood-based biomarker for detection of early-stage ovarian cancer." (PMID 36140519, 2022). "ADAM17 plays a role in the resistance of ovarian cancer cells to cisplatin." (PMID 36140519, 2022). "To find prognostic factors for advanced ovarian cancer patients undergoing first-line therapy with carboplatin, paclitaxel and bevacizumab, we investigated the expression of a disintegrin and metalloprotease 17 (ADAM17) in cancer tissues." (PMID 36140519, 2022). "Moreover, activation of ADAM17 by EGF increases ALCAM shedding by ovarian cancer cells and in vitro invasiveness." (PMID 36140519, 2022). "Multiple studies investigated ADAM17 tissue expression in ovarian cancer." (PMID 34771725, 2021). "Usage of ADAM17 in combination with CA-125 and other markers could help detect early stages of ovarian cancer." (PMID 34771725, 2021). "Since we confirmed the release of ADAM17 in the supernatant, we hypothesized that ADAM17 could also be detected in serum and cell-free ascites of ovarian cancer patients." (PMID 34771725, 2021). "ADAM17 appears to be a promising screening marker for detecting early-stage ovarian cancer." (PMID 34771725, 2021). "The detection of ADAM17 in serum has so far only been described for inflammatory diseases such as rheumatoid arthritis or endotoxic shock syndrome in sepsis, but not in connection with a malignant gynecological disease such as ovarian cancer." (PMID 34771725, 2021). "ADAM17 is physiologically located at the cell membrane, in vesicles or in the cytoplasm, therefore we firstly investigated, if ADAM17 can be detected in cell culture supernatants as a result of active or passive release from ovarian cancer cells." (PMID 34771725, 2021). "These initial results suggested that ADAM17 may be a suitable marker for the detection of ovarian cancer." (PMID 34771725, 2021). "Besides, a variety of ADAM17 substrates including the EGFR-ligands AREG and TGF-α were detected in patient-derived ascites of ovarian cancer patients, suggesting that ADAM17 is highly active in these patients." (PMID 29662625, 2018).
ovarian carcinoma (continued). "Thus, cisplatin increased ADAM17 downstream effector activation in all three ovarian cancer cell lines." (PMID 29662625, 2018). "Even though former approaches targeting ADAM17 was not successful in clinical trials due to the unspecific blockage of related metalloproteases, novel ADAM17-directed antibodies might be a promising tool for the treatment of ovarian cancer." (PMID 29662625, 2018). "Moreover, a recent study reported that a specific anti-ADAM17 antibody showed anti-tumor effects in an ovarian cancer model in vivo." (PMID 26993601, 2016). "Furthermore, we wanted to know whether, in ovarian cancer cells, the transition of these forms is controlled by proteases, i.e. ADAM10 or ADAM17, which had been associated with CX3CL1 cleavage in other cell systems before." (PMID 39862711, 2025). "Therefore, ADAM17 inhibition is considered a promising therapeutic strategy for ovarian cancer." (PMID 38069391, 2023). "Indeed, a recent study reported that the combined in vitro treatment with an ADAM17 inhibitor and cisplatin showed enhanced cytotoxicity in ovarian cancer spheroids in comparison with cisplatin monotherapy, thus proposing ADAM17 as an interesting target for combinatorial treatments." (PMID 36140519, 2022). "ADAM17-induced P75 cleavage may also be responsible for ovarian cancer-promoting activities." (PMID 36466812, 2022). "One study evaluating ADAM17 as a potential blood biomarker for ovarian cancer showed that ADAM17 levels are significantly higher in culture medium supernatants of cultured ovarian cancer cell lines and also in the serum and ascites of patients with ovarian cancer, compared with controls." (PMID 36591235, 2022). "Because of its high expression in tumors even in the early stages, the evaluation of ADAM17 as a potential blood-based screening marker for early detection of ovarian cancer seemed rational for us and will be examined more closely to potentially improve detection of ovarian cancer in earlier stages." (PMID 34771725, 2021). "Therefore, we tried to detect ADAM17 in serum samples of ovarian cancer patients." (PMID 34771725, 2021). "Since we measured elevated ADAM17 levels in patients suffering from ovarian cancer, we proceeded with investigating whether ADAM17 levels correlate with other clinical parameters, such as the FIGO stage, histological subtype, or the postoperative resection status." (PMID 34771725, 2021). "In addition, ADAM17 was found in serum and ascites of ovarian cancer patients." (PMID 34771725, 2021). "However, it is not well understood, whether and how ADAM17 might contribute to chemo resistance of ovarian cancer." (PMID 29662625, 2018). "Moreover, we investigated whether inhibition of ADAM17 can (re-)sensitize ovarian cancer cells to chemotherapeutic treatment." (PMID 29662625, 2018). "Thus, targeting ADAM17 in parallel to conventionally applied chemotherapy may represent a novel strategy to overcome resistance in ovarian cancer." (PMID 29662625, 2018). "Importantly, not only AREG levels were dramatically increased upon cisplatin treatment but protein amount of the metalloprotease ADAM17 itself also increased in the cisplatin-sensitive ovarian cancer cell lines Igrov-1 and A2780 as well as in ascites-derived primary cells." (PMID 29662625, 2018). "Indeed, ADAM17/TACE inhibitors reduced ovarian carcinoma cell motility in vitro." (PMID 21364949, 2011). "Accordingly, combined inhibition of ADAM17 and PARP leads to sensitivity in the treatment of ovarian cancer." (PMID 39506058, 2024). "To gain insight into the functional activity of ADAM17, we selected Nectin-4, HB-EGF and AREG as surrogate markers for ADAM17 activity and evaluated them as potential tumor markers for ovarian cancer." (PMID 36497350, 2022).